FBP1 (fructose-bisphosphatase 1)
Diseases named in the same sentence as FBP1 in open-access papers (continued):
Sharing a sentence is not in itself a finding about the gene and the disease.
pancreatic cancer (continued). "We have previously reported that FBP1 regulates the sensitivity of pancreatic cancer to various types of small molecules, including BET inhibitors, gemcitabine, MEK inhibitors, and AKT inhibitors." (PMID 34854226, 2022). "In this study, we aimed to understand how FBP1 regulates sensitivity to PARP inhibitors in pancreatic cancer." (PMID 34854226, 2022). "Collectively, we demonstrate that FBP1 regulates the sensitivity of pancreatic cancer to PARP inhibitors." (PMID 34854226, 2022). "FBP1‐specific short hairpin RNAs (shRNAs) were transfected into pancreatic cancer cells to construct FBP1 stable knockdown cells after puromycin selection." (PMID 34854226, 2022). "Given that the nuclear localization of FBP1 is critical for modulating the sensitivity to the PARP inhibitors we aimed to evaluate the effect of the FBP1‐K206R mutant on the response of pancreatic cancer to PARP inhibitors." (PMID 34854226, 2022). "Our study also revealed that PARP1 depletion attenuated the changes in PARP inhibitors sensitivity after knockdown or overexpression of FBP1 in pancreatic cancer cells." (PMID 34854226, 2022). "For instance, we showed that FBP1 interacted with BRD4 to enhance pancreatic cancer cell sensitivity to BET inhibitors." (PMID 34854226, 2022). "CBX3 has been found to be highly expressed and promote aerobic glycolysis by suppressing FBP1 in pancreatic cancer." (PMID 35210369, 2022). "In fact, downregulation of FBP1 was discovered in gastric carcinomas and gastric cancer cell lines and FBP1 was found to inhibit pancreatic cancer progression." (PMID 36430241, 2022). "NMP1, a multifaceted nucleolar protein, was found to stimulate glucose uptake and lactate generation in pancreatic cancer cells by directly inhibiting FBP1 expression." (PMID 29556139, 2018). "Restoring FBP1 in pancreatic cancer cells reversed the NPM1-induced dysfunction of glucose metabolism." (PMID 29556139, 2018). "Drug screening assay in Fructose-1, 6-biphosphatase (FBP1) knockdown or overexpressing pancreatic cancer cells was performed." (PMID 30201002, 2018). "In this study, we demonstrate that FBP1 promotes c-Myc degradation by inhibiting the MAPK pathway in pancreatic cancer cells." (PMID 30201002, 2018). "While, combined with our previous findings, the BET inhibitor increases FBP1 protein level which promoted c-Myc degradation in pancreatic cancer cells." (PMID 30201002, 2018). "In contrast, the protein level of FBP1 was lower in pancreatic cancer tissues compared to adjacent normal control tissues." (PMID 30201002, 2018). "NPM1 bound directly to the FBP1 promoter region to suppress the expression of FBP1 in pancreatic cancer cells." (PMID 30429463, 2018). "Meanwhile, we used a tissue microarray of human pancreatic cancer specimens obtained from a cohort of patients (n = 47 PDAC tissue specimens) to further examine the correlation between FBP1 and c-Myc at the protein level by IHC." (PMID 30201002, 2018). "The knockdown of FBP1 not only increased the pancreatic cancer cells viability, but also promoted PANC-1 cell resistant to JQ1 drug via decreasing the cleaved PARP expression and caspase-3 activity." (PMID 30201002, 2018). "FBP1 modulates the sensitivity of pancreatic cancer cells to BET inhibitors by decreasing the expression of c-Myc." (PMID 30201002, 2018). "Together, our data suggest that FBP1 modulates the sensitivity of BET inhibitors by decreasing the expression of c-Myc in pancreatic cancer." (PMID 30201002, 2018). "Co-treatment of FBP1-derived small peptide inhibitor FBP1 E4 enhanced the anti-cancer efficacy of gemcitabine in pancreatic cancer." (PMID 29556139, 2018). "NPM1 bound directly to the FBP1 promoter region to suppress the expression of FBP1 in pancreatic cancer." (PMID 29556139, 2018). "In pancreatic cancer, FBP1 expression impeded gemcitabine-induced ERK activation through inhibition of the IQGAP1-ERK1/2 signalling axis in a manner independent of its enzymatic activity." (PMID 29556139, 2018).
pancreatic cancer (continued). "FBP1 was consistently reported to be expressed at low levels in pancreatic cancer tissues; on the contrary, FBP1 was always at high level in normal pancreatic tissues." (PMID 29556139, 2018). "In sum, NPM1 promotes aerobic glycolysis and tumor progression in patients with pancreatic cancer by inhibiting FBP1." (PMID 26068981, 2015). "We also identified NPM1could stimulate aerobic glycolysis and repress fructose-1, 6-bisphosphatase 1 (FBP1) in pancreatic cancer cells." (PMID 26068981, 2015). "Tip60 and HDAC3 regulate the diacetylation of FBP1 in pancreatic cancer cells." (PMID 40100307, 2025). "It appears that targeting on ubiquitination of the TRIM47/FBP1 axis might develop a novel approach to suppress the worseness of pancreatic cancer." (PMID 40618019, 2025). "Previous research has reported that silencing CBX3 could inhibit aerobic glycolysis in pancreatic cancer by enhancing the expression of FBP1, a negative regulator of aerobic glycolysis." (PMID 39636180, 2024). "CBX3 promotes cancer cell proliferation by inhibiting the FBP1 gene in pancreatic cancer cells." (PMID 35573019, 2022). "Moreover, a subsequent study revealed that nuclear FBP1 interacted with DNMT1 to sensitize pancreatic cancer cells to PARP inhibitors, and this effect was independent of the enzymatic activity of FBP1." (PMID 34854226, 2022). "The specific mechanism by which FBP1 regulates the sensitivity of pancreatic cancer to Olaparib and whether FBP1 can modulate the sensitivity to Olaparib without affecting the HR pathway needs further study." (PMID 34854226, 2022). "Moreover, the subsequent co‐IP assay demonstrated that USP7 interacted with FBP1 reciprocally in pancreatic cancer cells." (PMID 34854226, 2022). "Therefore, our data suggested that DNMT1 was the binding partner of FBP1 in pancreatic cancer cells." (PMID 34854226, 2022). "Thus, our results indicated that FBP1 regulates the sensitivity of pancreatic cancer cells to Olaparib." (PMID 34854226, 2022). "Therefore, our results indicated that the USP7/FBP1 axis modulated the sensitivity of pancreatic cancer to PARP inhibitors." (PMID 34854226, 2022). "Here, we showed that FBP1 regulated the sensitivity of pancreatic cancer cells to PARP inhibitors." (PMID 34854226, 2022). "PARP inhibitors (such as Olaparib) are newly identified small molecules, and we aimed to investigate whether FBP1 contributed to the response of pancreatic cancer cells to this agent." (PMID 34854226, 2022). "Thus, degradation of FBP1 enhances the Warburg effect by promoting glycolysis, and contributes to the progression of pancreatic cancer." (PMID 35954308, 2022). "Here, we also found that FBP1 could trap PARP1 on chromatin, which might be one of the explanations for how FBP1 regulates the sensitivity of pancreatic cancer to PARP inhibitors." (PMID 34854226, 2022). "Moreover, CCK‐8, caspase 3 activity, and Annexin V/PE assays demonstrated that FBP1 knockdown resulted in pancreatic cancer cell resistance to Olaparib in vitro." (PMID 34854226, 2022). "Our findings in this study suggest that JQ1 increases FBP1 stability through disrupting the interaction between FBP1 and TRIM28, which suggest JQ1 might be an ideal small molecular to increase the FBP1 expression and repress pancreatic cancer." (PMID 30201002, 2018). "Fructose-1, 6-biphosphatase (FBP1) is a rate-limiting enzyme in gluconeogenesis that converts fructose-1, 6-bisphosphate to fructose-6-phosphate and negatively regulates aerobic glycolysis in pancreatic cancer cells." (PMID 30201002, 2018). "We demonstrated that FBP1 increased the sensitivity of pancreatic cancer to JQ1." (PMID 30201002, 2018). "The expression of FBP1 protein increased the sensitivity of pancreatic cancer cells to JQ1." (PMID 30201002, 2018). "Moreover, we showed that JQ1 stabilized FBP1 protein level in pancreatic cancer cells, and subsequently promoted c-Myc degradation through the disruption of the ERK-c-Myc axis." (PMID 30201002, 2018).
pancreatic cancer (continued). "However, the molecular mechanisms by which FBP1 antagonizes cancer chemoresistance in pancreatic cancer warrant further investigation." (PMID 29556139, 2018). "FBP1 is responsible for the sensitivity of treatment with BET inhibitors in pancreatic cancer." (PMID 30201002, 2018). "Indeed, the downregulation of FBP1 leads to tumor progression and poor prognosis in pancreatic cancer, and this is also the case in various types of tumor." (PMID 30201002, 2018). "To further demonstrate that FBP1 is a critical target gene involved in the NPM1-induced phenotypes of pancreatic cancer cells, we over-expressed FBP1 and NPM1 in the Bxpc-3 cell lines, and effective restoration of FBP1 expression in Bxpc3 cells was confirmed by qRT-PCR." (PMID 26068981, 2015). "Fourth, restore the FBP1 in pancreatic cancer cells could reverse the NPM1-induced glucose metabolism dysfunction." (PMID 26068981, 2015). "However, the knockdown of FBP1 seemed to reduce the basal apoptosis in pancreatic cancer cells, which might contribute to determining the sensitivity of PARP inhibitors." (PMID 34854226, 2022). "Therefore, an up-regulation of FBP1 in pancreatic cancer might provide an ideal strategy to inhibit the pancreatic cancer cell progression." (PMID 30201002, 2018). "Therefore, we want to determine whether FBP1 participates in modulating the expression of c-Myc in pancreatic cancer." (PMID 30201002, 2018). "Therefore, FBP1 functions as a tumor suppressor in pancreatic cancers." (PMID 30201002, 2018). "FBP1 downregulates the levels of the BRD4 target genes WNT5a, FLRT2, and PDE9A, and partially inhibits pancreatic cancer through BRD4 progression." (PMID 40100307, 2025). "In pancreatic cancer, CBX3 downregulates FBP1 expression and promotes glycolysis, while the CDK4/6-E2F1 pathway increases MAGED1 expression and promotes FBP1 degradation, and the CDK4/6 inhibitor PD0332991 eliminates the Warburg effect." (PMID 40100307, 2025). "According to studies, JQ1 disturbs the link between TRIM28 and FBP1, improving FBP1 protein levels, and FBP1 increases c-Myc degradation by blocking the MAPK pathway, making pancreatic cancer more sensitive to JQ1." (PMID 40100307, 2025). "In pancreatic cancer, USP7 deubiquitinates fructose-1,6-bisphosphatase 1 (FBP1) at K206, hindering its nuclear translocation." (PMID 38702734, 2024). "Here, we showed that FBP1 translocated into the nucleus and bound to DNA (cytosine‐5)‐methyltransferase 1 (DNMT1) to modulate the sensitivity of pancreatic cancer cells to PARP inhibitors." (PMID 34854226, 2022). "In the cytoplasm, FBP1 was found to bind with IQGAP1 to inactivate the MAPK pathway and sensitize pancreatic cancer cells to gemcitabine." (PMID 34854226, 2022). "To this end, we knocked down endogenous FBP1 using two independent shRNAs in PANC-1 and MIA PaCa-2 pancreatic cancer cell lines." (PMID 31938049, 2020). "It has previously been reported that FBP1 inhibits the IQGAP1–ERK interaction and decreases the phosphorylation of ERK1/2 in pancreatic cancer." (PMID 30201002, 2018). "JQ1 reduces the ubiquitination of FBP1 by disrupting the interaction between FBP1 and TRIM28, suggesting that JQ1 may be an ideal small molecule to increase FBP1 expression and inhibit pancreatic cancer." (PMID 40100307, 2025). "In contrast, when WT FBP1 and G260R enzymatically dead mutants were transfected into MIA PaCa‐2 and Capan‐1 cells, overexpression of FBP1 sensitized the pancreatic cancer cells to Olaparib, which was independent of its glucogenic activity." (PMID 34854226, 2022). "Similarly, in pancreatic cancer, CBX3 was reported to promote cell proliferation and regulate aerobic glycolysis by suppressing FBP-1." (PMID 36140750, 2022). "As USP7 is responsible for the subcellular distribution of FBP1 but does not influence the stability of FBP1 in pancreatic cancer cells, we were curious about how USP7 regulates this process." (PMID 34854226, 2022).
pancreatic cancer (continued). "Furthermore, we showed that FBP1 bound to STAT3 and prevented STAT3 phosphorylation, which modulated the immune response and PD‐L1 antibody blockade efficiency in pancreatic cancer cells." (PMID 34854226, 2022). "It is worth noting that FBP1 could bind to the WW domain of IQGAP1 and block IQGAP1-dependent ERK1/2 phosphorylation in pancreatic cancer." (PMID 30201002, 2018). "FBP1 overcame gemcitabine resistance and inhibited extracellular regulated protein kinases (ERK) activation by blocking IQ motif containing GTPase-activating protein 1 (IQGAP1)–mitogen-activated protein kinase (MAPK) interaction in pancreatic cancer cells." (PMID 30429463, 2018). "Furthermore, we showed that JQ1 stabilized FBP1 protein level by disrupting the interaction between FBP1 and TRIM28 in pancreatic cancer cells." (PMID 30201002, 2018). "Thus, our data suggest that FBP1 promotes c-Myc degradation through the inhibition of the ERK pathway in pancreatic cancer cells, and the BET inhibitor downregulates c-Myc partially via stabilizing FBP1 in pancreatic cancer cells." (PMID 30201002, 2018). "To investigate the clinical relevance of FBP1 in regulating c-Myc protein levels in pancreatic cancer patients, we assessed both c-Myc and FBP1 protein levels in 8 non-tumor and tumor-paired human pancreatic cancer specimens." (PMID 30201002, 2018). "UBR5-induced aerobic glycolysis is dependent on FBP1 in pancreatic cancer cells and there is a significant negative correlation between the levels of UBR5 and FBP1." (PMID 40630951, 2025). "We showed that JQ1 treatment increased FBP1 protein level but not the mRNA level in dose-and time- dependent manners in both PANC-1 and SW1990 pancreatic cancer cells." (PMID 30201002, 2018).
lung carcinoma (20 papers, 2018 to 2025). "It has been suggested that upregulation of the gluconeogenic enzyme Fructose-1,6-bisphosphatase 1 (FBP1) in NK cells of lung cancer, which inhibits their glycolytic metabolism, is caused by high levels of TGF-β in the TME." (PMID 34079545, 2021). "In the current study, we determined the underlying mechanism for FBP1 expression suppression and its biological functions in lung cancer cells." (PMID 29984231, 2018). "Decreased levels of FBP1 expression were associated with poor prognosis in lung cancer patients." (PMID 37737707, 2023). "On the other hand, we found that the lower methylation of FBP1 in cancer tissues is associated with better overall survival for lung cancer patients, indicating a potential of methylation level in FBP1 promoter as a novel predictor for prognosis in non-small cell lung cancer patients." (PMID 29984231, 2018). "β-Elemene induced apoptosis in gefitinib-resistant lung cancer cells through the FBP1/STAT3 axis, which inhibited cancer cell growth and increasing sensitivity to gefitinib." (PMID 40100307, 2025). "The binding of ZEB1 to the FBP1 promoter was reported to increases DNA methylation in lung cancer cells." (PMID 40100307, 2025). "DNA methylation in the promoter region helps reduce FBP1 expression in lung cancer cells, and in turn, the downregulation of FBP1 leads to lung cancer cell growth and invasion." (PMID 40100307, 2025). "Research has reported that elevated levels of FBP1 are linked to a better prognosis in various tumor diseases including renal cancer, gastric cancer, and lung cancer, suggesting that FBP1 acts an essential part in cancer glucose metabolism." (PMID 40100307, 2025). "GBE1, while traditionally linked to glycogen metabolism, has emerged as a tumor progression factor through its involvement in NF-κB-mediated FBP1 methylation in lung cancer." (PMID 41049004, 2025). "In contrast, autopsy samples from pulmonary bulla or lung cancers (stated as Control group) that were pathologically confirmed to be inflammation-free demonstrated only FBP1+ macrophages." (PMID 39414783, 2024). "This study presents evidence that FBP1 plays a crucial role in regulating lung cancer stem cells, and that NICD1 is necessary for FBP1-mediated maintenance of the CSC phenotype." (PMID 38349431, 2024). "An increasing body of evidence suggests that FBP1, SBK1 and AURKA are associated with lung cancer progression." (PMID 37737707, 2023). "Our research indicated that β‐elemene suppressed proliferation and enhanced sensitivity to gefitinib by inducing apoptosis through the FBP1/STAT3 axis in gefitinib‐resistant lung cancer cells." (PMID 36525508, 2023). "The NCBI‐Gene database was used to investigate the potential roles of these genes in lung cancer, and FBP1 was selected for further investigation." (PMID 36525508, 2023). "In vivo experiments further confirmed the enhanced effects of FBP1 on lung cancer cell sensitivity to gefitinib." (PMID 36525508, 2023). "Based on the fact that knockdown of CBX3 results in an upregulation of FBP1 in pancreatic cells and upregulation of FOXM1 results in a decrease in FBP1 expression in lung cancer, it seems the simulation is indeed correct." (PMID 35404841, 2022). "Overexpression of FBP1 in lung cancer cells decreases glucose uptake, consequently decreasing lactate production." (PMID 35404841, 2022). "For example, dysfunction of NK cells can be caused by induction of the glycolysis-inhibiting enzyme fructose-bisphosphatase 1 (FBP1) which leads to tumor progression in KRAS-driven models of lung cancer." (PMID 33995422, 2021). "Adoptive transfer of NK cells treated with MB05032, an FBP1 inhibitor that restores NK cell glycolysis and effector functions, slows tumor growth in a lung cancer model in mouse." (PMID 34079545, 2021). "In human lung cancer tissues, FBP1 mRNA and proteins were found to poorly express when compared to paired normal lung tissues." (PMID 29556139, 2018).